DCST2 (DC-STAMP domain containing 2)
Description:
Essential sperm cell-surface protein required for sperm-egg fusion and fertilization.
Synonyms: FLJ32934; SPE42
Tractability: Antibody: UniProt predicts a signal peptide or a membrane-spanning region.
Gene: Protein-coding gene on chromosome 1 (155,018,520 to 155,033,781, reverse strand). Ensembl gene ENSG00000163354.
Subcellular location: Cytoplasmic vesicle, secretory vesicle, acrosome membrane
Gene Ontology:
Biological process: fusion of sperm to egg plasma membrane involved in single fertilization; sperm-egg recognition
Cellular component: acrosomal membrane; membrane
Genetic constraint (gnomAD): Loss-of-function variants: 64 observed, 83.77 expected, observed/expected ratio (o/e) 0.76, 90% interval 0.62 to 0.94. The upper end of that interval is the gene's LOEUF score, 0.94, which puts it in group 3 of 6, group 1 being the genes least tolerant of losing a copy. Missense variants: 945 observed, 1,038.1 expected, observed/expected ratio (o/e) 0.91, 90% interval 0.86 to 0.96. Synonymous variants: 354 observed, 419.08 expected, observed/expected ratio (o/e) 0.84, 90% interval 0.77 to 0.92.
Homologues: Orthologues: chimpanzee DCST2 (99% identical), macaque DCST2 (98% identical), guinea pig DCST2 (71% identical), rat Dcst2 (69% identical), mouse Dcst2 (66% identical), zebrafish dcst2 (34% identical), Drosophila melanogaster CG6845 (22% identical), Drosophila melanogaster CG32320 (15% identical). Paralogues in human: DCST1 (21% identical), OCSTAMP (12% identical), DCSTAMP (11% identical).
Diseases named in the same sentence as DCST2 in open-access papers:
DCST2 is named in the same sentence as 4 diseases in open-access papers, as found by Europe PMC text mining. Sharing a sentence is not in itself a finding about the gene and the disease. The quoted sentences say what the papers report.
Infertility (1 paper, 2024). "Eight genes that result in male infertility (IZUMO1, SPACA6, TMEM95, TMEM81, SOF1, FIMP, DCST1, and DCST2) and an additional two that cause infertility in females (JUNO and CD9) have been identified." (PMID 38381819, 2024).
tumor (2 papers, 2021 to 2023). "The genes expression levels in the model were detected by qRT-PCR, and the results showed that they were highly expressed in 20 pairs of tumor and normal tissues (UNCX, SLC6A3, AGAP2-AS1, LINC00968, PTX3 and SBSPON), while ITPRID1, DCST2, ETV3L, and ENSG00000261327 were down-regulated." (PMID 36647156, 2023).
DCST2 also shares sentences with these, for which no sentence is quoted: male infertility (1 paper); prostate carcinoma (1).